FAM78A (family with sequence similarity 78 member A)
Synonyms: C9orf59; FLJ00024
Tractability: PROTAC: ubiquitination databases record sites on it; its protein half-life has been measured.
Gene: Protein-coding gene on chromosome 9 (131,258,076 to 131,277,365, reverse strand). Ensembl gene ENSG00000126882.
Subcellular location (Human Protein Atlas): Nucleoplasm; Vesicles
Gene Ontology:
Molecular function: protein binding
Genetic constraint (gnomAD): Loss-of-function variants: 11 observed, 21.91 expected, observed/expected ratio (o/e) 0.5, 90% interval 0.31 to 0.83. The upper end of that interval is the gene's LOEUF score, 0.83, which puts it in group 3 of 6, group 1 being the genes least tolerant of losing a copy. Missense variants: 311 observed, 386.06 expected, observed/expected ratio (o/e) 0.81, 90% interval 0.73 to 0.88. Synonymous variants: 145 observed, 149.12 expected, observed/expected ratio (o/e) 0.97, 90% interval 0.85 to 1.12.
Homologues: Orthologues: chimpanzee FAM78A (99% identical), macaque FAM78A (99% identical), dog FAM78A (97% identical), mouse Fam78a (97% identical), rat Fam78a (97% identical), pig FAM78A (96% identical), guinea pig FAM78A (94% identical), rabbit FAM78A (94% identical), tropical clawed frog fam78a (72% identical), zebrafish fam78ab (66% identical). Paralogues in human: FAM78B (66% identical).
Diseases named in the same sentence as FAM78A in open-access papers:
FAM78A is named in the same sentence as 2 diseases in open-access papers, as found by Europe PMC text mining. Sharing a sentence is not in itself a finding about the gene and the disease.
FAM78A shares sentences with these, for which no sentence is quoted: pancreatic cancer (1 paper); tumor (1).